ADA (adenosine deaminase)
Diseases named in the same sentence as ADA in open-access papers (continued):
Sharing a sentence is not in itself a finding about the gene and the disease.
lymphoma (continued). "The use of a smaller ADA cut-point lead to seven false positive TB cases (2 systemic erythematous lupus, 2 lymphomas, 1 poorly differentiated cancer, 1 empyema, 1 undefined diagnosis) that could have been diagnosed with PlTB if it was considered alone." (PMID 30148839, 2018). "According to the preceding text, 3 potentially challenging scenarios could be envisioned in clinical practice, namely the differentiation of malignant and TB effusions, lung adenocarcinomas from mesotheliomas, and lymphomas with falsely elevated ADA from TB." (PMID 26962828, 2016). "Finally, in the third, cathepsin-B was able to discriminate 12 lymphomas with high ADA levels from 12 TB with 100% sensitivity (95% CI 73.5–100%) and 83.3% specificity (95% CI 51.6–98%)." (PMID 26962828, 2016). "In addition, an increased level of pleural ADA levels are also found in other etiologies, such as rheumatoid pleural effusion, bacterial pleural infection, mesothelioma, lung cancer, leukaemia, empyema, and lymphoma." (PMID 34034670, 2021). "Our case and review of the literature suggests the possibility that pleural effusate adenosine deaminase levels in patients with primary effusion lymphoma-like lymphoma (PEL-LL) might be much higher than those in patients with other types of lymphomas and those with tuberculous pleural effusion." (PMID 33363910, 2020). "The lack of ADA would be expected to decrease the oncogenic risk since ADA inhibitors have been used for the treatment of lymphomas and the accumulation of adenosine and purine metabolites in ADA-deficient patients leads to increased apoptosis in T and B cells." (PMID 29456531, 2018). "Furthermore, although a higher ADA level in pleural fluid is considered to be associated with a greater chance of TPE, most patients with UPPE and CPPE have a pleural ADA level of around 40 U/L or below, and an extremely high ADA level should raise a suspicion of empyema or lymphoma." (PMID 29202740, 2017). "However, elevated ADA in ascites has rarely been reported in the diagnosis of lymphoma." (PMID 24711934, 2014). "The lymphoma-specific tracer 18F-Fludarabine, targeting the enzyme adenosine deaminase, has exhibited improved specificity compared to FDG in distinguishing lymphoma from inflammatory conditions, potentially reducing false-positive findings." (PMID 40265016, 2025). "Although higher ADA levels have traditionally been associated with a higher likelihood of TBP, recent studies have reported that extremely high ADA levels may indicate a low probability of TBP and that the possibility of lymphoma should be considered in diagnosis." (PMID 38178065, 2024). "ADA can be elevated in different noninfectious conditions associated with pleural and peritoneal fluid lymphocytosis, including malignancies (adenocarcinomas, leukemias, and lymphomas) and connective tissue diseases (rheumatoid arthritis, systematic lupus erythematosus)." (PMID 24711934, 2014). "Therefore, when ADA and LDH were increased simultaneously, it was necessary to broaden our thinking and be alert to the possibility of lymphoma." (PMID 40766055, 2025). "In a report by Porcel and colleagues in Spain, among 22 patients presenting with pleural ADA levels exceeding 250 IU/L, 19 were diagnosed with empyema, 3 with lymphoma, and none with TBP." (PMID 38178065, 2024). "Adenosine deaminase (ADA) inhibition not only may be applied for the treatment of ischemic injury, hypertension, lymphomas and leukaemia, but also they have been considered as anti- inflammatory drugs." (PMID 23351306, 2012). "For instance, an extremely high ADA activity is highly suggestive of lymphoma rather than TPE." (PMID 29308081, 2017). "In patients of advanced age, false-negative results may occur with ADA, whereas misdiagnosis may occur with higher ADA levels when differentiating from bacterial pleural infections (particularly complex PPE and empyema) and lymphoma." (PMID 38750432, 2024).
rheumatoid arthritis (30 papers, 2012 to 2026). A chronic, systemic autoimmune disorder characterized by inflammation in the synovial membranes and articular surfaces. "Similarly, ADA levels are associated with disease activation in patients with other autoimmune diseases, such as systemic lupus erythematosus, juvenile idiopathic arthritis, rheumatoid arthritis, and Still’s disease." (PMID 34149447, 2021). "The interactions of the target compounds (the ligand and complexes) with the Mus musculus ADA enzyme structure (PDB ID: 1a4m), which causes rheumatoid arthritis, were estimated by applying the molecular docking studies." (PMID 40542123, 2025). "The results indicate that purified quercetin shows promising potential as an anti-inflammatory agent in the treatment of rheumatoid arthritis by inhibiting the activity of the adenosine deaminase enzyme." (PMID 39858545, 2025). "Elevated adenosine deaminase has been observed in patients with rheumatoid arthritis, and the enzyme can be cleaved by mast cell-released CPA3 to produce PAMP-12." (PMID 39144634, 2024). "In a 12-week open-label study on patients with rheumatoid arthritis, methotrexate was also reported to enhance adenosine-induced vasodilation (determined by forearm blood flow measurement and adenosine deaminase activity in erythrocytes and lymphocytes)." (PMID 36899991, 2023). "ADA has also been proposed as a biomarker and possible therapeutic target for a number of inflammatory conditions, including rheumatoid arthritis, cardiovascular disease, inflammatory bowel disease, and bacterial infection." (PMID 36031900, 2022). "ADA2 activity has also been studied in a number of adult rheumatic conditions and increased adenosine deaminase activity is observed in individuals with rheumatoid arthritis (RA), systemic lupus erythematous (SLE), and Crohn’s disease." (PMID 32650798, 2020). "ADA is ubiquitous to almost all human tissues, and ADA abnormalities have been reported in various diseases, including rheumatoid arthritis." (PMID 30444912, 2018). "In furthermore, 269 Caucasian patients with HS and 365 with rheumatoid arthritis treated with ADA were evaluated to see if HLA type was linked to a lack of response to ADA." (PMID 35035485, 2022). "ADA modulates purinergic responses to several pathophysiological events, such as rheumatoid arthritis (RA), chronic pulmonary diseases, sepsis, and inflammatory bowel diseases." (PMID 32438744, 2020). "Moreover, correlations between the increases of ADA levels and other inflammatory markers such as C-reactive protein (CRP) have been reported in diseases with inflammatory components such as gestational diabetes mellitus or rheumatoid arthritis." (PMID 28594948, 2017). "ADA is also a nonspecific inflammatory and immune response marker for TB, such as higher false-negative rates in individuals with liver cirrhosis or HIV infection and false-positive rates in patients with malignancy-related fluid, bacterial pneumonia or pulmonary empyema, and rheumatoid arthritis." (PMID 35965614, 2022).
chronic granulomatous disease (24 papers, 2009 to 2025). Chronic granulomatous disease (CGD) is a rare primary immunodeficiency, mainly affecting phagocytes, which is characterized by an increased susceptibility to severe and recurrent bacterial and fungal infections, along with the development of granulomas. "It is not totally clear why the LTR-containing MLV vector caused insertional oncogenesis in SCID-X1 but not ADA-SCID, but similar insertional oncogenesis in patients treated for chronic granulomatous disease and Wiskott–Aldrich syndrome suggests that ADA deficiency offers some intrinsic protection." (PMID 26702034, 2015). "Therapy using retroviral vectors has been demonstrated to be an efficient treatment for different disorders, including X-linked SCID (SCID-X1), chronic granulomatous disease (CGD), and adenosine deaminase-deficient SCID." (PMID 33499096, 2021). "IKBKB deficiency, adenosine-deaminase severe combined immune deficiency (SCID), and chronic granulomatous disease were the most common IEI." (PMID 40061245, 2025). "Diseases that have been corrected by gene therapy include X-linked severe combined immunodeficiency (X-linked SCID), adenosine deaminase severe combined immunodeficiency (ALD), and X-linked chronic granulomatous disease (CGD)." (PMID 21914224, 2011). "Gene therapy holds promise for the cure of various inherited and acquired diseases, as evidenced by the success in the treatment of X-linked severe combined immunodeficiency (SCID-X1), adenosine deaminase (ADA) deficiency and chronic granulomatous disease (CGD)." (PMID 19649289, 2009). "Gamma retroviral vectors were used as delivery vectors in early clinical trials for gene therapy of IEIs, including ADA-SCID, X-linked SCID (X-SCID), Wiskott–Aldrich syndrome (WAS), and X-linked chronic granulomatous disease (X-CGD)." (PMID 37051232, 2023). "The gene therapy has been proven clinically efficient in targeting X-linked severe combined immune deficiency (X-SCID), adenine deaminase deficiency SCID (ADA-SCID), and chronic granulomatous disease (CGD)." (PMID 35399522, 2022). "In the past years, a number of PIDs, including severe combined immune deficiencies (SCIDs: X-SCID, ADA-SCID), Wiskott–Aldrich syndrome (WAS), chronic granulomatous disease (CGD), and X-linked hyper-IgM (X-HIM) have been effectively treated by conventional gene addition-based approaches." (PMID 34198536, 2021). "Recently, the proteomic panel was expanded to eight signature peptide biomarkers to screen for five molecularly defined IEI including adenosine deaminase (ADA) deficiency, dedicator of cytokinesis 8 (DOCK8) deficiency, X-Linked chronic granulomatous disease (XL-CGD), WAS, and XLA." (PMID 34842618, 2021).
tuberculous meningitis (24 papers, 2006 to 2025). "Clinically, increased cerebrospinal fluid (CSF) adenosine deaminase (ADA) level is an important diagnostic clue of tuberculous meningitis." (PMID 28028491, 2016). "Raised CSF ADA (10 IU/L) was strongly associated with bacterial and tubercular meningitis." (PMID 34020719, 2021). "While elevated levels of ADA have been associated with typhoid fever, infectious mononucleosis, tuberculous meningitis (differentiates tuberculous from viral lymphocytic meningitis), AIDS, rheumatoid arthritis, psoriasis, pneumonia, chronic diarrhoea and widespread skin rashes." (PMID 33883834, 2020). "Rural residence (aOR 4.1, 95% CI 1.214.4) and raised CSF ADA (10 IU/L) (aOR 25.5, 95% CI 3.1212) were associated with bacterial meningitis when compared with viral meningitis; similarly, raised CSF ADA (10 IU/L) (aOR 42.2, 95% CI 2.0882) was associated with tubercular meningitis." (PMID 34020719, 2021). "Similarly, rural residence, raised CSF protein, lower CSF/blood glucose ratio, and raised ADA level were associated with tubercular meningitis in the univariate analysis; however, only raised ADA level was associated independently with tubercular meningitis as compared to viral meningitis." (PMID 34020719, 2021). "Clinically, increased cerebrospinal fluid (CSF) adenosine deaminase (ADA) level is an important diagnostic clue of tuberculous meningitis (TBM)." (PMID 28028491, 2016). "A recent meta-analysis reported that adenosine deaminase has a sensitivity of 89% and specificity of 91% for diagnosing tuberculous meningitis." (PMID 40400662, 2025). "‡Similarly, as no reference range for cerebrospinal fluid ADA was established at our institution, we referred to a study that reported ADA levels of 1-4 IU/L to be useful in excluding tuberculous meningitis." (PMID 40416201, 2025). "It was shown that ADA levels from cerebrospinal fluids of patients diagnosed with TB meningitis were higher than those diagnosed with bacterial meningitis." (PMID 39623309, 2024). "The certainty of evidence shown by our GRADE analysis was found to be of very low quality both for the sensitivity and specificity of cerebrospinal fluid adenosine deaminase to diagnose tuberculous meningitis." (PMID 37404432, 2023). "An elevated adenosine deaminase (ADA) level in the cerebrospinal fluid (CSF) is considered a reliable marker of tuberculous meningitis (TBM)." (PMID 35865825, 2022). "In the present study CSF - ADA level 10 U/L as a cut-off value differentiate tuberculous from non-tuberculous meningitis." (PMID 21629544, 2010). "The random-effect model in terms of pooled sensitivity, specificity, and diagnostic odds ratio (DOR) with 95% confidence interval was adopted to derive the diagnostic efficacy of cerebrospinal fluid (CSF) adenosine deaminase (ADA) for the diagnosis of tuberculous meningitis (TBM) in adult patients." (PMID 37404432, 2023). "Similarly, the CSF analysis showed higher WBC count, protein level, and ADA levels in bacterial and tubercular meningitis than viral meningitis." (PMID 34020719, 2021). "Clinical features and CSF findings can mimic tuberculous meningitis, except for ADA levels." (PMID 23799119, 2013). "In both pleural TB and TB meningitis, ADA tests had higher sensitivity than any other tests." (PMID 21629524, 2010). "In addition, 5 (16.6%) of our 30 autoimmune GFAP-A patients had; therefore, the possibility of autoimmune GFAP-A, in addition to tuberculous meningitis, should be taken into consideration by the clinicians when in the presence of elevated CSF adenosine deaminase." (PMID 37153594, 2023). "Hence ADA levels may be helpful in differentiating scrub meningitis from tuberculous meningitis but more studies are necessary in that direction." (PMID 23799119, 2013). "CSF adenosine deaminase (ADA), Mycobacterium tuberculosis PCR and nucleic acid amplification (NAA) tests help in the diagnosis of tubercular meningitis." (PMID 31485120, 2019).
tuberculous meningitis (continued). "Although the utility of the CSF ADA was also limited due to its low sensitivities, however, because the CSF ADA was convenient and inexpensive and had a specificity of 0.91 (95% CI: 0.89–0.93), it might assist in excluding tuberculous meningitis during differential diagnosis." (PMID 26503802, 2015). "In addition, serum markers such as ADA and CRP in CSF have been investigated for their ability to aid in the diagnosis of tuberculous meningitis, particularly in children." (PMID 40486653, 2025). "For example, in CSF, with three microbiological tests negative but ADA positive, the probability of TB meningitis was only 33%, but the probability of ATT was 96% (26/27 patients)." (PMID 35706064, 2022). "ADA level is also increased in nontuberculous meningitis, but it is marked significantly increased in tuberculous meningitis." (PMID 33467582, 2021). "Although non-tuberculous meningitis could raise the CSF ADA levels, non-infectious neurological diseases do not commonly increase it." (PMID 36867276, 2023). "Tests such as the adenosine deaminase assay (ADA) have been evaluated and may be used as an aid in diagnosis; however, they are not specific enough to differentiate TB meningitis from other forms of bacterial meningitis." (PMID 24197880, 2014).
diabetes (23 papers, 2012 to 2025). "In addition, increasing evidence has highlighted that ADA is associated with increased levels of hemoglobin (HbA1c), which plays a critical role in the derangement of lipogenesis in diabetes." (PMID 35893142, 2022). "Accordingly, in this study we evaluated the effect diabetes/hyperglycemia, considered the main cause of diabetes complications, have on the expression and protein levels of adenosine receptors and of the enzymes adenosine deaminase (ADA) and adenosine kinase (AK)." (PMID 23840723, 2013). "A recent cross-sectional study found that serum ADA levels were significantly increased in uncontrolled diabetes (HbA1c > 7%) when compared to healthy controls and controlled diabetes (HbA1c < 7%), and were significantly positive correlated with FPG and HbA1c." (PMID 34001220, 2021). "The recruited participants had normal serum ADA levels of 13.6 (11.1–16.9) U/L, diabetes duration of 78.64 ± 74.45 months, ages of 58.17 ± 13.12 years, BMI of 25.75 ± 3.58 kg/m2 and HbA1c levels of 9.02 ± 4.43%." (PMID 34001220, 2021). "Defect in insulin activity required for T-lymphocytes in diabetes leads to abnormal T-lymphocyte proliferation and enhanced ADA activity." (PMID 28050278, 2016). "ADA alongside other immunomodulatory enzymes acts as a deconstructive oxidative marker in diabetes and plays an important role in progression of its complications." (PMID 28050278, 2016). "The increase of adenosine level with decrease in adenosine kinase in diabetes results in deamination of adenosine and the increase in adenosine deaminase." (PMID 28050278, 2016). "Insulin deficiency and irregulation of glucose are major factors in the elevation of ADA in diabetes." (PMID 28050278, 2016). "We also observed a decrease in mRNA and protein levels of ADA and AK in retinas 30 days after diabetes induction." (PMID 23840723, 2013). "Adenosine deaminase and adenosine kinase expression and protein levels showed a significant decrease in diabetic retinas 30 days after diabetes induction." (PMID 23840723, 2013). "The role of inflammation being minimal in the pathogenesis of type 2 diabetes mellitus (T2DM) in nonobese patients; the aim of the study was to investigate the role of adenosine deaminase (ADA) and see its association with diabetes mellitus." (PMID 24453844, 2013). "Recently it was found that NOD mice express increased levels of ADA promoting autoreactive T cell activation and diabetes development." (PMID 22514744, 2012). "Elevated ADA levels have been observed in various inflammatory conditions, including diabetes mellitus, where it may contribute to the chronic inflammatory state that characterizes the disease." (PMID 39493017, 2024). "Recent studies have indicated that ADA may be involved in the pathogenesis of diabetes and its complications, making it a candidate biomarker for assessing the risk of microvascular complications in T2DM patients." (PMID 39493017, 2024). "Interestingly, serum levels of ADA isoenzymes are significantly elevated in both insulin-dependent diabetes mellitus and non-insulin-dependent diabetes mellitus patients compared to healthy controls." (PMID 38092892, 2023). "We also show that ADA is influenced by hypertension, diabetes, and lifestyle." (PMID 36260871, 2022). "Therefore, costimulatory signaling between CD26 and ADA would be preserved facilitating further T cell activation and T cell-dependent complications of diabetes." (PMID 33053898, 2020). "ADA increased activity was reported in the lymph nodes and splenocyte of diabetes-prone BB rats." (PMID 28050278, 2016). "However, after 30 days of diabetes induction it was observed a marked decrease in AK and ADA protein levels: AK levels decreased to 85.03±3.95% of control (p<0.05), and ADA levels were down to 71.8±6.4% of control (p<0.01)." (PMID 23840723, 2013).